SNORD12B (small nucleolar RNA, C/D box 12B)
Gene: Small nucleolar RNA gene on chromosome 20 (49,280,319 to 49,280,409, forward strand). Ensembl gene ENSG00000222365.
Gene Ontology:
Biological process: RNA processing
Cellular component: nucleolus
Homologues: Orthologues: chimpanzee SNORD12B (100% identical), macaque SNORD12B (99% identical), dog SNORD12B (95% identical), guinea pig SNORD12B (91% identical), rat Gm23201 (80% identical), mouse Gm23201 (78% identical). Paralogues in human: SNORD12C (69% identical), SNORD12 (65% identical).
Diseases named in the same sentence as SNORD12B in open-access papers:
SNORD12B is named in the same sentence as 7 diseases in open-access papers, as found by Europe PMC text mining. Sharing a sentence is not in itself a finding about the gene and the disease. The quoted sentences say what the papers report.
glioma (1 paper, 2021). A benign or malignant brain and spinal cord tumor that arises from glial cells (astrocytes, oligodendrocytes, ependymal cells). "We next explored the expression of SNORD12B in different glioma tissues, NHAs, and the U251 and U373 cell lines by qRT‐PCR." (PMID 34047477, 2021). "The expression of SNORD12B was higher in glioma tissues of different grades compared with that in NBTs, and its expression level was progressively upregulated with increasing pathological grade." (PMID 34047477, 2021). "Finally, our in vivo study revealed that MSI2 knockdown, SNORD12B knockdown, or ZBTB4 overexpression suppressed xenograft glioma tumor growth and was associated with prolonged survival." (PMID 34047477, 2021). "We found that SNORD12B expression was upregulated in glioma tissues and U251 and U373 cells." (PMID 34047477, 2021). "MSI2 and SNORD12B expression was significantly increased and ZBTB4 expression was decreased in glioma tissues and cells." (PMID 34047477, 2021). "The present study revealed the oncogenic nature of MSI2 and SNORD12B and the antioncogenic role of ZBTB4 in glioma." (PMID 34047477, 2021). "Further, mice injected with a combination of the three showed minimal xenograft glioma volume and the longest survival time compared with those in the MSI2 knockdown, SNORD12B knockdown, or ZBTB4 overexpression group." (PMID 34047477, 2021). "Thus, the MSI2/SNORD12B/FIP1L1/ZBTB4 positive feedback loop plays a crucial role in regulating the glycolipid metabolism of GBM cells and provides a potential drug target for glioma treatment." (PMID 34047477, 2021).
tumor (2 papers, 2018 to 2021). "To confirm the roles of MSI2, SNORD12B, and ZBTB4 in tumor growth in vivo, we subcutaneously injected GBM MSI2(−) cells, SNORD12B(−) cells, ZBTB4(+) cells, or a combination of the three cells to construct mouse xenograft models." (PMID 34047477, 2021).
SNORD12B also shares sentences with these, for which no sentence is quoted: breast carcinoma (1 paper); cancer (1); colon cancer (1); glioblastoma (1); pancreatic cancer (1).